CAPN14 (calpain 14)
Description:
Calcium-regulated non-lysosomal thiol-protease.
Tractability: No criterion of Open Targets' tractability assessment is met for any kind of drug.
Gene: Protein-coding gene on chromosome 2 (31,173,056 to 31,234,011, reverse strand). Ensembl gene ENSG00000214711.
Pathways (Reactome):
Extracellular matrix organization: Degradation of the extracellular matrix
Gene Ontology:
Molecular function: calcium-dependent cysteine-type endopeptidase activity; calcium ion binding
Biological process: proteolysis
Cellular component: cytoplasm
Genetic constraint (gnomAD): Loss-of-function variants: 82 observed, 88.88 expected, observed/expected ratio (o/e) 0.92, 90% interval 0.77 to 1.11. The upper end of that interval is the gene's LOEUF score, 1.11, which puts it in group 4 of 6, group 1 being the genes least tolerant of losing a copy. Missense variants: 774 observed, 799.47 expected, observed/expected ratio (o/e) 0.97, 90% interval 0.91 to 1.03. Synonymous variants: 320 observed, 314.57 expected, observed/expected ratio (o/e) 1.02, 90% interval 0.93 to 1.12.
Homologues: Orthologues: chimpanzee CAPN14 (99% identical), macaque CAPN14 (94% identical), dog CAPN14 (80% identical), pig CAPN14 (79% identical), tropical clawed frog capn14 (47% identical), zebrafish zgc:136872 (37% identical), zebrafish si:ch211-202f3.3 (35% identical), zebrafish si:ch211-202f3.4 (29% identical), zebrafish zgc:162184 (28% identical), Caenorhabditis elegans clp-7 (27% identical), Caenorhabditis elegans clp-1 (27% identical), Caenorhabditis elegans clp-6 (27% identical), and 5 more. Paralogues in human: CAPN11 (40% identical), CAPN3 (39% identical), CAPN8 (38% identical), CAPN9 (38% identical), CAPN1 (37% identical), CAPN2 (37% identical), CAPN12 (35% identical), CAPN13 (34% identical), CAPN5 (26% identical), CAPN6 (25% identical), CAPN10 (24% identical), CAPN7 (22% identical), and 8 more.
Diseases named in the same sentence as CAPN14 in open-access papers:
CAPN14 is named in the same sentence as 15 diseases in open-access papers, as found by Europe PMC text mining. Sharing a sentence is not in itself a finding about the gene and the disease. The quoted sentences say what the papers report.
asthma (2 papers, 2020 to 2023). "Notably, PSES hypomethylate ALOX15, CAPN14, and POSTN asthma genes which increases the prevalence of asthma symptoms." (PMID 36960908, 2023).
eosinophilic esophagitis (2 papers, 2022 to 2026). Eosinophilic esophagitis (EoE) is a chronic, allergic disease of the esophagus characterized clinically by symptoms of esophageal dysfunction (including vomiting, dysphagia, feeding disorders, food impaction and abdominal pain) which persist after treatment with proton pump inhibitors (PPIs). "CAPN14 is thought to play a regulatory role in the esophageal epithelium, with overexpression impairing barrier function and SNPs in this locus having been associated with susceptibility to the allergic inflammatory disease eosinophilic esophagitis and middle ear infection." (PMID 35254093, 2022).
allergic asthma (1 paper, 2019). A asthma with a basis in a pathological type I hypersensitivity reaction. "Namely, for environment IgE sensitization (METTL1), for allergic asthma (NTRK1), and several for FeNO (MAP3K14, NTRK1, FBXL7, PCSK6, SLC9A3, CDH26, CAPN14, and MAP3K14)." (PMID 31300640, 2019).
allergic disease (1 paper, 2025). An immune response that occurs following re-exposure to an innocuous antigen, and that requires the presence of existing antibodies against that antigen. "Though CAPN14 likely contributes to the tissue specificity of EoE, the EoE risk genes TSLP, EMSY, LRRC32, and CLEC16A are hypothesized to have roles in numerous allergic diseases." (PMID 40470207, 2025). "Importantly, the MTAG approach did not replicate the 2p23 (CAPN14) EoE risk locus, consistent with the lack of association at this locus with other allergic diseases." (PMID 40470207, 2025).
bacteremia (1 paper, 2022). "We identify SNPs within the genes CAPN14 and MIATNB as having P < 10−5 for association with development of enteric fever symptoms or bacteremia following exposure." (PMID 35254093, 2022). "While the study was underpowered to detect any single nucleotide polymorphisms (SNPs) significant at the whole-genome level, two SNPs within CAPN14 and MIATNB were identified with P < 10−5 for association with development of symptoms or bacteremia following oral S. Typhi or S. Paratyphi A challenge." (PMID 35254093, 2022).
cholesteatoma (1 paper, 2012). A pathologic process characterized by the proliferation of keratinizing squamous epithelium resulting in the accumulation of keratin and cells in the middle ear and/or mastoid. "For example, CAPN14 is a member of the calpain family of cytosolic calcium-activated cysteine proteases, other members of which mediate host cell invasion by known otopathogens and are up-regulated in cholesteatoma associated with OM and its sequelae, including OME, COME and chronic suppurative OM." (PMID 23133572, 2012).
endometriosis (1 paper, 2017). The growth of functional endometrial tissue in anatomic sites outside the uterine body. "Of these eight loci, three were associated with all endometriosis (LAMC3, CAPN14 and DEFA1), and six with Stage B disease (NAALADL2, NR2C1, C14orf132, FOXP2, CDH20 and LAMC3)." (PMID 28333195, 2017).
meningioma (1 paper, 2023). A generally slow growing tumor attached to the dura mater. "Six antigens were exclusively found in the immunopeptidome of WHO grade I meningiomas (CAPN14, KIR2DS4, TMM44, ECD, CD86, and RFWD3), whereas WHO grade I and III meningiomas showed only one antigen in common (KLC2)." (PMID 37368072, 2023).
infection (3 papers, 2012 to 2024). The state of being infected such as from the introduction of a foreign agent such as serum, vaccine, antigenic substance or organism. "CAPN14 is up-regulated in human conjunctival epithelial cells by interleukin-4, a key T helper 2 cytokine involved in infection control and allergic responses." (PMID 23133572, 2012). "Apoptosis related proteins (ANXA5 and Caspase-13/CASP4) and CAPN14, USP18, XAF1, Caspase-13/CASP4, and ISG12 transcripts were significantly upregulated after infection with swH1N1 compared to controls." (PMID 39247193, 2024). "The frequency of expression of CAPN14 and DSG1 was similar between the negative pre-infection and the negative control group." (PMID 36482106, 2022).
tumor (3 papers, 2023 to 2025). "Spatial transcriptomic mapping showed that the CAPN14 gene was predominantly highly expressed in specific tissue regions with clustered distribution, reaching a maximum expression density of 0.3, mainly concentrated in tumor core areas and certain marginal zones." (PMID 41395113, 2025).
cancer (1 paper, 2021). A tumor composed of atypical neoplastic, often pleomorphic cells that invade other tissues. "Few studies evaluated the relationship between cancer progression and LIN7A or CAPN14 expression." (PMID 34158601, 2021).
CAPN14 also shares sentences with these, for which no sentence is quoted: heart disease (1 paper); middle ear infection (1); Obesity (1); stenosis (1).